GATA2 (GATA binding protein 2)
Description:
Transcriptional activator which regulates endothelin-1 gene expression in endothelial cells. Binds to the consensus sequence 5'-AGATAG-3'.
Synonyms: NFE1B; DCML; IMD21; MONOMAC
Tractability: PROTAC: UniProt records ubiquitination sites on it; ubiquitination databases record sites on it.
Target class: Transcription factor
Gene: Protein-coding gene on chromosome 3 (128,479,423 to 128,493,208, reverse strand). Ensembl gene ENSG00000179348.
Subcellular location: Nucleus
Subcellular location (Human Protein Atlas): Nucleoplasm
Pathways (Reactome):
Developmental Biology: Transcriptional regulation of granulopoiesis
Gene expression (Transcription): RUNX1 regulates transcription of genes involved in differentiation of HSCs
Hemostasis: Factors involved in megakaryocyte development and platelet production
Gene Ontology:
Molecular function: C2H2 zinc finger domain binding; chromatin binding; DNA-binding transcription factor activity; DNA-binding transcription factor activity, RNA polymerase II-specific; protein binding; RNA polymerase II-specific DNA-binding transcription factor binding; sequence-specific double-stranded DNA binding; transcription coregulator binding; RNA polymerase II cis-regulatory region sequence-specific DNA binding; DNA binding; DNA-binding transcription activator activity, RNA polymerase II-specific; sequence-specific DNA binding; transcription coactivator binding; zinc ion binding
Biological process: eosinophil fate commitment; fat cell differentiation; negative regulation of endothelial cell apoptotic process; negative regulation of gene expression; negative regulation of neural precursor cell proliferation; negative regulation of Notch signaling pathway; positive regulation of angiogenesis; positive regulation of blood vessel endothelial cell migration; positive regulation of blood vessel endothelial cell proliferation involved in sprouting angiogenesis; positive regulation of cell migration involved in sprouting angiogenesis; positive regulation of gene expression; positive regulation of miRNA transcription; positive regulation of transcription by RNA polymerase II; vascular wound healing; cell fate commitment; negative regulation of transcription by RNA polymerase II; positive regulation of phagocytosis; anatomical structure morphogenesis; cell differentiation; cochlea development; neuron migration; positive regulation of cytosolic calcium ion concentration; positive regulation of DNA-templated transcription; positive regulation of mast cell degranulation; positive regulation of neuron differentiation; and 6 more
Cellular component: cytoplasm; nucleoplasm; nucleus; transcription regulator complex
Genetic constraint (gnomAD): Loss-of-function variants: 6 observed, 35.36 expected, observed/expected ratio (o/e) 0.17, 90% interval 0.092 to 0.34. The upper end of that interval is the gene's LOEUF score, 0.34, which puts it in group 1 of 6, group 1 being the genes least tolerant of losing a copy. Missense variants: 541 observed, 663.34 expected, observed/expected ratio (o/e) 0.82, 90% interval 0.76 to 0.88. Synonymous variants: 313 observed, 280.9 expected, observed/expected ratio (o/e) 1.11, 90% interval 1.01 to 1.22.
Gene-disease validity (ClinGen):
ClinGen rates the evidence that GATA2 causes each of these diseases.
GATA2 deficiency with susceptibility to MDS/AML (autosomal dominant): Definitive. A disorder arising from deficiency in the GATA2 with a wide spectrum of phenotypes.
Cancer hallmarks: suppression of growth (promotes); invasion and metastasis (promotes); angiogenesis (promotes); proliferative signalling (promotes); invasion and metastasis (suppresses); escaping programmed cell death (promotes); escaping immune response to cancer
Homologues: Orthologues: chimpanzee GATA2 (100% identical), macaque GATA2 (99% identical), dog GATA2 (99% identical), pig GATA2 (99% identical), mouse Gata2 (98% identical), rat Gata2 (98% identical), tropical clawed frog gata2 (84% identical), zebrafish gata2a (71% identical), guinea pig GATA2 (69% identical), Drosophila melanogaster srp (30% identical), Drosophila melanogaster GATAd (24% identical), Caenorhabditis elegans elt-2 (15% identical), and 1 more. Paralogues in human: GATA3 (61% identical), GATA1 (35% identical), GATA6 (32% identical), GATA4 (30% identical), GATA5 (29% identical), TRPS1 (24% identical), ZGLP1 (9% identical).
Diseases named in the same sentence as GATA2 in open-access papers:
GATA2 is named in the same sentence as 338 diseases in open-access papers, as found by Europe PMC text mining. Sharing a sentence is not in itself a finding about the gene and the disease. The quoted sentences say what the papers report.
acute myeloid leukemia (98 papers, 2009 to 2026). Acute myeloid leukemia (AML) is a group of neoplasms arising from precursor cells committed to the myeloid cell-line differentiation. "Two SNPs within the GATA2, rs2335052 and rs78245253, are associated with an increased risk of acute myeloid leukemia (AML) in Chinese populations." (PMID 40650116, 2025). "GATA2 dysregulation is associated with myelodysplastic syndromes (MDSs) and acute myeloid leukemia (AML), where it promotes leukemic stem cell self-renewal and impedes myeloid differentiation." (PMID 41514651, 2025). "Mutations in the guanine-adenine-thymine-adenine 2 (GATA2) gene can lead to immunodeficiency and haematological diseases, including acute myeloid leukaemia (AML)." (PMID 40797383, 2025). "Here, we present follow up to a case of a woman with acute myeloid leukemia and lifelong thrombocytopenia which had previously been attributed to presumptive pathogenic (P) GATA2 missense variants." (PMID 40148527, 2025). "Dendritic cell, monocyte, B and NK lymphoid deficiency, (MonoMAC) syndrome: monocytopenia and mycobacterial infections, familial myelodysplastic syndrome and acute myeloid leukemia have been described by GATA2 mutations." (PMID 41438140, 2025). "For instance, one of the true positives predicted by PolyPhen-2, “GATA2:p.R398W”, is associated with acute myeloid leukemia and alveolar proteinosis." (PMID 39253604, 2024). "We report a 36‐year‐old woman with germline GATA2‐deficiency who developed Merkel cell carcinoma followed by acute myeloid leukemia." (PMID 39614632, 2024). "Exploration of variant allele frequency (VAF) of GATA2 mutations (GATA2mut) provides insights into acute myeloid leukemia (AML) prognosis." (PMID 38416121, 2024). "Any mutation or impairment in the GATA2 gene results in GATA2 deficiency, presenting several distinct syndromes in the dendritic cell, monocyte, B, natural killer lymphoid deficiency, acute myeloid leukemia, and natural killer (NK) cell deficiency." (PMID 38956704, 2024). "Heterozygous GATA2 coding or enhancer germline mutations cause GATA2 deficiency syndrome involving immunodeficiency, myelodysplastic syndrome, and acute myeloid leukemia." (PMID 36809258, 2023). "A study found that haploinsufficiency of GATA2 underlies primary lymphedema and predisposes to acute myeloid leukaemia." (PMID 36980710, 2023). "The mutation of GATA2 is associated with a variety of genetic and immune diseases, including myelodysplastic syndrome and acute myeloid leukemia." (PMID 35743172, 2022). "Heterozygous deletions of GATA2, which has been recognized as an acute myeloid leukemia (AML) predisposition gene, promote EVI1-provoked leukemic transformation." (PMID 35087776, 2021). "PubMed search was performed using a combination of keywords ‘GATA2’, ‘deficiency’, ‘mutation’, ‘familial’, ‘acute myeloid leukaemia’, ‘myelodysplastic syndrome’, ‘Emberger-syndrome’ and ‘MonoMac’." (PMID 34633564, 2021). "Loss and gain of GATA2 expression has been implicated in myelodysplastic syndrome and acute myeloid leukemia (AML) yet the precise biological impact of GATA2 expression on human AML cell fate decisions remains ambiguous." (PMID 31434974, 2019). "Patients with GATA2 mutation have a high risk of developing myelodysplastic syndrome or acute myeloid leukemia." (PMID 31035956, 2019). "Given the patient’s family history and clinical manifestation, this was interpreted as an acute myeloid leukemia with heritable GATA2 mutations associated with familial AML-MDS." (PMID 24754962, 2014). "Heritable GATA2 mutations associated with familial myelodysplastic syndrome and acute myeloid leukemia have only been described recently." (PMID 24754962, 2014).
acute myeloid leukemia (continued). "In patients with acute myeloid leukaemia, GATA-2 was rather associated with poor prognosis, although this correlation is challenged by a recent report." (PMID 19707195, 2009). "GATA2 is overexpressed in acute myeloid leukemia (AML) and loss-of-function mutations have been causally linked to immunodeficiency associated with the myelodysplastic syndromes (MDS), suggesting that an appropriate level of GATA2 activity is a prerequisite for normal hematopoiesis." (PMID 29029492, 2017). "Following efforts focused on understanding SV-induced enhancer hijacking and enhancer activation loss, for example at the EVI1/GATA2 locus in acute myeloid leukemias (AML) carrying inversions or translocations of chromosome 3." (PMID 40840919, 2025). "TET2 and GATA2 are two frequently co-mutated genes in CEBPA double mutated acute myeloid leukemia (AML)." (PMID 37794021, 2023). "Deregulation of the EVI1 proto-oncogene by the GATA2 distal hematopoietic enhancer (G2DHE) is a key event in high-risk acute myeloid leukemia carrying 3q21q26 aberrations (3q-AML)." (PMID 33911178, 2021). "These syndromes are characterized by monocytopenia, neutropenia, B-, dendritic- and NK cell lymphopenia and up to 80% of patients with innate GATA2 mutations develop myelodysplastic syndrome (MDS)/ acute myeloid leukemia (AML)." (PMID 34633564, 2021). "GATA2 has critical functions in the hematopoietic system, and the mutation of GATA2 could result in hematopoietic and immune defects, leading to the occurrence of acute myelocytic leukemia." (PMID 30935420, 2019). "Other studies have demonstrated that elevated levels of GATA2 and Xvent2 are strongly associated with myeloid cell differentiation and acute myeloid leukemia (AML) progression in human cells." (PMID 30061699, 2018). "The GATA2 c.1084C>T variant has specifically been reported to be associated with MDS, acute myeloid leukaemia (AML), and IEI." (PMID 40264496, 2025). "In 2011, a 50-year-old woman was diagnosed with acute myeloid leukemia (AML) with monosomy 7, and was reported to have GATA2 deficiency after molecular profiling on blood identified two germline GATA2 variants (p.Thr358Lys and p.Leu359Val) in the second zinc finger which were found to reside in cis." (PMID 40148527, 2025). "Patients with GATA2 deficiency are predisposed to developing myelodysplastic neoplasms (MDS), which can progress to acute myeloid leukemia." (PMID 41249190, 2025). "GATA2 has been identified as a predisposition gene for familial myelodysplastic syndrome (MDS) with a high propensity to evolve into acute myeloid leukemia (AML)." (PMID 40299403, 2025). "Multilineage cytopenias involving NK cells, B cells and monocytes are common and characteristic of GATA2 haploinsufficiency, as is progression to myelodysplastic syndrome and acute myeloid leukemia, which suggests early HSCT would be beneficial." (PMID 39267745, 2024). "GATA2 was found to be mediated by p38/ERK-dependent phosphorylation in acute myeloid leukemia cells and to be involved in the transcriptional regulation of several pro-inflammatory cytokines, including IL-1β." (PMID 37208193, 2023). "GATA2 deficiency is a complex disorder associated with an increased risk for myelodysplastic syndrome (MDS) and acute myeloid leukemia." (PMID 38067298, 2023). "In the case of Acute Myeloid Leukemia, there are two variations (GATA2:c.1061 C>T and GATA2:c.1192C>T) with contradictory interpretations." (PMID 37946154, 2023). "Translocations between 3q21 and 3q26.2 have been observed in patients with acute myeloid leukemia, repositioning an enhancer located upstream of the GATA2 gene within the telomeric side TAD." (PMID 37426677, 2023). "Approximately 20% to 25% of adults with acute myeloid leukemia have mutations involving the myeloid transcription factors Runt-related transcription factor 1 (RUNX1), CEBPA, and/or GATA binding protein 2 (GATA2)." (PMID 37047003, 2023).
acute myeloid leukemia (continued). "GATA2 deficiency is a heterogeneous, multisystem disorder associated with a high risk of developing myelodysplastic syndrome (MDS) and the progression to acute myeloid leukemia." (PMID 38067298, 2023). "This is illustrated in our study by the co-occurrence of a GATA2 variant and a CNV aberration of chromosome 8, which is indicative for acute myeloblastic leukemia." (PMID 32373116, 2020). "Coding and noncoding GATA2 mutations cause GATA2-deficiency syndromes, which often involve immunodeficiency and predisposition to develop myelodysplastic syndrome (MDS) and acute myeloid leukemia (AML) (15, 44, –, 48)." (PMID 32241909, 2020). "Germline loss-of-function mutations in the GATA2 gene are associated with myelodysplastic syndrome (MDS), acute myeloid leukaemia (AML) and opportunistic infections, including NTM infections." (PMID 31035956, 2019). "Several acute myeloid leukemia (AML) predisposition syndromes are caused by innate mutations in transcription factors that affect embryonic hematopoiesis, such as Gata2 and Runx1, suggesting that perturbations in embryonic hematopoiesis affect the adult HSC compartment." (PMID 30374440, 2018). "Our finding that ACY-957 increases GATA2 expression has therapeutic implications beyond hemoglobinopathies, as GATA2 haploinsufficiency has been linked to a variety of disorders, including myelodysplastic syndrome (MDS) and acute myeloid leukemia (AML)." (PMID 27073918, 2016). "Several previous studies have demonstrated the influence of GATA2 expression levels on the clinical outcome in patients with pediatric acute myeloid leukemia (AML), colorectal, prostate, breast cancer, and hepatocellular carcinoma." (PMID 26287967, 2015). "Germline GATA2 mutations are involved in a group of complex syndromes with overlapping clinical features of immune deficiency, lymphedema and propensity to acute myeloid leukemia or myelodysplastic syndrome (AML-MDS)." (PMID 24754962, 2014). "GATA2 is also involved in the development of bladder and breast cancer and acute myelogenous leukemia." (PMID 23202957, 2012). "Additionally, two GATA-2 mutations (Δ341–346 and L359V), affecting the second zinc-finger domain and conferring either reduced or increased transcriptional activity, respectively, have recently been described in patients progressing from chronic to acute myeloid leukaemia.." (PMID 21297973, 2011). "GATA2, a transcription factor essential for hematopoiesis and immune function, has been associated with a range of clinical manifestations, including immunodeficiency, myelodysplastic syndromes (MDS), and acute myeloid leukemia (AML)." (PMID 41154393, 2025). "The indication for transplantation was based on the pathogenic heterozygous GATA2 nonsense variant, which is predicted to result in premature truncation of the GATA2 protein and is associated with MonoMAC syndrome, myelodysplastic syndrome (MDS), and acute myeloid leukemia (AML) predisposition." (PMID 41438140, 2025). "For hematological malignancies, hereditary predisposition was first identified in chronic lymphocytic leukemia (CLL) and acute myeloid leukemia (AML), which has led to the identification of several germline mutations, such as RUNX1, CEBPA, GATA2, ANKRD26, DDX41 and ETV6 mutations." (PMID 36998465, 2023). "Therefore, we propose that reducing GATA2 expression or inhibition of its transcription activity can relieve the drug resistance of acute myeloid leukemia cells and it would be helpful for eliminating the leukemia cells in patients." (PMID 28114350, 2017). "Inactivating mutations in GATA2 were identified as responsible for Emberger syndrome, an autosomal dominant primary lymphedema that is associated with a predisposition to acute myeloid leukemia (AML), as well as in familial myelodysplastic syndrome/AML or MonoMAC syndrome and primary lymphedema." (PMID 22922986, 2013).